MFSD8 (major facilitator superfamily domain containing 8)
Description:
Outward-rectifying chloride channel involved in endolysosomal chloride homeostasis, membrane fusion and function. Conducts chloride currents up to hundreds of picoamperes. Regulates lysosomal calcium content by reducing the lysosomal membrane potential, thereby activating TRPML1 channel and further release of lysosomal calcium ions. Regulates the pH in endolysosomal compartments and may contribute to progressive acidification from endosome to lysosome. Permeable to other halides such as iodide and fluoride ions.
Synonyms: CLN7; SLC74A1; MGC33302; CCMD
Tractability: Antibody: UniProt places it where antibodies can reach, with high confidence; UniProt predicts a signal peptide or a membrane-spanning region. PROTAC: its protein half-life has been measured.
Gene: Protein-coding gene on chromosome 4 (127,917,799 to 127,966,034, reverse strand). Ensembl gene ENSG00000164073.
Subcellular location: Endosome membrane; Lysosome membrane
Subcellular location (Human Protein Atlas): Vesicles; Nucleoplasm
Gene Ontology:
Molecular function: chloride channel activity; fluoride channel activity; iodide transmembrane transporter activity; transmembrane transporter activity
Biological process: autophagosome maturation; lysosome organization; chloride transmembrane transport; fluoride transmembrane transport; inorganic anion transport; iodide transport; transmembrane transport
Cellular component: endosome membrane; lysosomal membrane; lysosome; membrane; mitochondrion; vacuole
Genetic constraint (gnomAD): Loss-of-function variants: 39 observed, 50.69 expected, observed/expected ratio (o/e) 0.77, 90% interval 0.6 to 1. The upper end of that interval is the gene's LOEUF score, 1, which puts it in group 4 of 6, group 1 being the genes least tolerant of losing a copy. Missense variants: 485 observed, 565.18 expected, observed/expected ratio (o/e) 0.86, 90% interval 0.8 to 0.93. Synonymous variants: 179 observed, 199.13 expected, observed/expected ratio (o/e) 0.9, 90% interval 0.8 to 1.02.
Gene-disease validity (ClinGen):
ClinGen rates the evidence that MFSD8 causes each of these diseases.
neuronal ceroid lipofuscinosis (autosomal recessive): Definitive.
Homologues: Orthologues: chimpanzee MFSD8 (97% identical), macaque MFSD8 (95% identical), dog MFSD8 (86% identical), pig MFSD8 (86% identical), guinea pig MFSD8 (83% identical), mouse Mfsd8 (82% identical), rat Mfsd8 (81% identical), rabbit MFSD8 (81% identical), tropical clawed frog mfsd8 (64% identical), zebrafish mfsd8 (60% identical), Drosophila melanogaster Cln7 (35% identical), Caenorhabditis elegans mfsd-8 (26% identical), and 8 more. Paralogues in human: SLC75A1 (14% identical), SLC71A1 (14% identical), SLC67A2 (13% identical), SLC71A2 (12% identical), MFSD1 (11% identical), SLC61A1 (10% identical).